CXCL12 (C-X-C motif chemokine ligand 12)
Diseases named in the same sentence as CXCL12 in open-access papers (continued):
Sharing a sentence is not in itself a finding about the gene and the disease.
endometrial cancer (18 papers, 2010 to 2026). Primary or metastatic malignant neoplasm involving the endometrium (mucous membrane that lines the endometrial cavity). "Cancer-associated fibroblasts derived from endometrial cancer also secrete CXCL12 and its high levels were associated with poor prognosis." (PMID 34768458, 2021). "The mutual interaction between TGF-β1 and CXCL12 led to the increased tumorigenesis, invasion, migration, and EMT of endometrial cancer cells in vitro and in vivo, which can be reversed by neutralizing antibodies of either CXCL12 or CXCR4." (PMID 38049868, 2023). "CXCL12/CXCR4 also has essential roles in the muscular infiltration of endometrial cancer by activating the PI3K/Akt signalling pathway." (PMID 37509322, 2023). "Another study showed that TGF‐β secreted by endometrial cancer cells induces CXCL12 production by endometrial mesenchymal stem cells." (PMID 36300800, 2023). "The CXCL12/CXCR4 axis plays a vital role in endometrial cancer’s proliferation, invasion, and metastasis." (PMID 37509322, 2023). "α-smooth muscle actin (α-SMA), another mesenchymal marker, was found to be increased in endometrial cancer cells with CXCR4/CXCL12 treatment." (PMID 36766756, 2023). "Overexpression of CXCL12 in endometrial cancer compared to the control observed in our study is consistent with previous reports." (PMID 34768458, 2021). "It has been observed that as endometrial cancer progresses, expression of CXCL12, GNAL, OPRK1, DRD2, and DRD3 increases while DRD5 and COMT levels are gradually reduced." (PMID 34768458, 2021). "As far as endometrial cancer, studies on CXCR4 and CXCL12 expression revealed that CXCR4 is overexpressed in endometrial cancers as compared with normal tissues, whereas CXCL12 was overexpressed in normal mucosa." (PMID 20049170, 2010). "In endometrial cancer, the CXCL12/CXCR4 axis induces proliferation and invasion." (PMID 34322132, 2021). "High levels of miR-135b-5p have also been reported in endometrial cancer, however there has been no information about its association with CXCL12 so far." (PMID 34768458, 2021). "N-cadherin was over expressed when endometrial cancer cells were treated with TGF-β, IL-6, chemokines CCL18, RANK/RANKL/CCL20, and CXCR4/CXCL12." (PMID 36766756, 2023). "Expression of CXCL12, OPRK1, DRD5, COMT, DRD2, and DRD3 proteins was assessed in the serum of endometrial cancer patients and control group using ELISA." (PMID 34768458, 2021). "Along similar lines, the En-MSC could indirectly interact with endometrial cancer cells (RL95-2, HEC-1-A, and Ishikawa), promoting both En-MSC and cancer cells to reciprocally secret TGF-β1 and CXCL12." (PMID 38049868, 2023).
infarction (18 papers, 2014 to 2025). A localised pathological necrosis of tissue resulting from obstruction of the blood supply usually by a thrombus, an embolus, or vascular torsion. "Intracardiac or intramyocardial injection of CXCL12 reduced infarction size and increased cardiac function after MI/IRI and MI, and cardioprotective effects were blocked with AMD3100." (PMID 24966838, 2014). "The activation of the CXCR4/CXCL12 axis was found to play an important role in angiogenesis as well as the homing and mobilization of progenitor cells; this then results in the development of CVDs, including myocardial ischemia and infarction." (PMID 36979628, 2023). "In a qPCR analysis, increased levels of angiopeptin, CXCL12, HIF-1α and miR-132 were found 24 h after cell-based gene delivery, compared to those in untreated animals with infarction and in control animals." (PMID 35646882, 2022).
Arthritis (17 papers, 2005 to 2024). Inflammation of a joint. "Another association of BTK to disease (arthritis) via the CXCL12 signaling pathway can be seen by BTK’s involvement in mediating osteoclast differentiation and bone resorption activity in a CIA mouse model that can be blocked by an antagonist to BTK." (PMID 34803999, 2021). "Lyz1, Dnajc15, Nfkbia, Cxcl12, Ccl21a, and Cxcl13 are considered to be arthritis-associated gene." (PMID 33752715, 2021). "The CXCL12/CXCR7 axis in synovial tissue plays an important role in the development of arthritis." (PMID 35165253, 2022). "Mammalian target of rapamycin complex 1 (mTORC1) is a protein complex that controls protein synthesis, and activation of mTORC1 in subchondral preosteoblasts promotes arthritis by stimulating bone sclerosis (abnormal hardening) and secreting C-X-C motif chemokine 12 (CXCL12)." (PMID 30792936, 2019). "To collect further evidence for the hypothesis that AMD3100 protects mice from arthritis by blocking CXCL12-mediated leukocyte mobilization, we ascertained that CXCL12-elicited migration of immunocompetent cells to inflamed sites does take place during CIA development." (PMID 16277673, 2005). "We also quantified CXCL12 and CXCL13 levels in the serum at the same time point of arthritis." (PMID 38691538, 2024). "In addition, several transcripts with known roles in arthritis were positionally enriched in specific joint locations including MMP1, MMP13, interleukin (IL) 1R, IL34 and CXCL12 (refs 17, 18, 19, 20)." (PMID 28332497, 2017).
colitis (17 papers, 2012 to 2025). Inflammation of the colon. "Several genes encoding chemokines, including CCL21, and 25, and CXCL12, 14, and 15, showed gradually decreased expression during the development of colitis, indicative of a changing chemotactic profile during the progression of colon inflammation." (PMID 23226271, 2012). "Using a murine model of dextran sulfate sodium (DSS)-induced colitis, the study further demonstrates that CXCR4 expression is elevated on leukocytes and that CXCL12 expression increases in colonic tissue when colitis is induced." (PMID 39070795, 2024). "Blocking the CXCL12/CXCR4 axis ameliorates experimental colitis in a murine model, indicating a crucial role in the intestinal inflammatory response." (PMID 35363937, 2022). "According to previous studies, blockade of the CXCL12/CXCR4 axis by the specific antagonist AMD3100 attenuates experimental colitis in a murine model by inhibiting chronic inflammation and enhancing epithelial barrier integrity." (PMID 35363937, 2022). "We identified CXCL12 as a direct target of miR‐126 in inhibiting the development of colitis and CAC." (PMID 35363937, 2022). "We identified CXCL12 as a target gene of miR‐126 in inhibiting the development of colitis and CAC." (PMID 35363937, 2022). "This reduction in CXCL12 expression subsequently inhibits macrophage functions, including migration to the tumour site and secretion of the proinflammatory cytokine IL‐6, to suppress colitis and tumorigenesis." (PMID 35363937, 2022). "Loss of intestinal epithelial Ihh or a lack of Smo in Hh target cells made the animals more sensitive to DSS-induced colitis, while activation of Ihh sequesters C-X-C motif chemokine ligand 12 (CXCL12) in fibroblasts, thus damaging immune cell migration and inhibiting the immune response." (PMID 34702800, 2021). "Consequently, NLRP12-deficient mice were highly susceptible to colitis and colitis-associated colorectal cancer through the increase in noncanonical NF-κB activation and expression of Cxcl13 and Cxcl12 as target genes that were associated with cancer." (PMID 34571825, 2021). "In this line, CXCR4 in response to SDF-1 (CXCL12), or CX3CR1 in response to CX3CL1, have been tested in preclinical models of colitis." (PMID 34829736, 2021). "The expressions of ICAM-1, IL-1β, IL-16, CXCL10, MCP-1, CXCL9, CXCL12, and TIMP-1 were greatly reduced in MSC-EX-treated colitis group compared with those in the PBS-treated colitis group." (PMID 28842625, 2017).
Hyperglycemia (17 papers, 2008 to 2025). An increased concentration of glucose in the blood. "Induction of CXCR4 and CXCL12 expression in EPCs with cysteine-rich angiogenic inducer 61 (CCN1) can reverse hyperglycemia-induced impaired mobilization of EPCs." (PMID 40308758, 2025). "CXCL12 is inhibited in hyperglycemia, neointima formation is blocked, and M2-type macrophages cannot produce cytokines that promote angiogenesis." (PMID 40308758, 2025). "The local application of lactic acid bacteria transformed with a CXCL12-expressing plasmid accelerated wound closure in healthy mice, in mouse models of hyperglycemia and peripheral ischemia, as well as in an ex vivo model of human skin." (PMID 32718071, 2020). "Hyperglycemia induces increased CXCL12 production by the PSCs, and its receptor, CXCR4 on cancer cells." (PMID 26010611, 2015). "Persistent hyperglycemia inhibits CXCL12 expression in diabetic wounds." (PMID 40308758, 2025). "Hyperglycemia leads to an enhanced expression of chemokines in kidney tissue, such as CCL2, CCL3, CCL4, CCL5, and CXCL12, involving in immune cell recruitment and modulating the inflammation." (PMID 40046045, 2025). "For example, hyperglycemia can stimulate the secretion of CCL2, CCL5, and CXCL12, through podocytes and tubular cells, as reported in mouse models and DN patients, which contributes to proteinuria and glomerulosclerosis." (PMID 34221188, 2021).
Insulin resistance (17 papers, 2015 to 2025). Increased resistance towards insulin, that is, diminished effectiveness of insulin in reducing blood glucose levels. "Other studies, however, proposed a detrimental role of CXCL12 in adipose tissue inflammation and insulin resistance as well as in microvascular diabetic complications." (PMID 39109081, 2024). "Although the results in diverse populations have been controversial, it is accepted that CXCL12 is a protein that promotes the secretion of proinflammatory cytokines and the development of insulin resistance." (PMID 30764545, 2019). "Interestingly, the cold regulation of Cxcl12 was specific to BAT, and did not occur in the other adipose depots examined, where CXCL12 has been associated with WAT inflammation and insulin resistance in mice." (PMID 39848402, 2025).
liver cancer (17 papers, 2016 to 2025). An epithelial or non-epithelial malignant neoplasm that arises from the liver. "SOX18 promotes the accumulation of Tregs and immunosuppressive tumor-associated macrophages (TAMs) in the liver cancer microenvironment by transactivating PD-L1 and CXCL12." (PMID 39889187, 2025). "Studies have demonstrated that fucoidan modulates the CXCL12/CXCR4 axis, exerting a dose-dependent inhibitory effect on Huh7 liver cancer cells by reducing CXCL12 expression." (PMID 39206194, 2024). "Studies have found that overexpression of SOX4 regulates the CXCL12 promoter in liver cancer cells to enhance tumor-induced angiogenesis, which contributes to distant tumor metastasis and causes poor prognosis in liver cancer patients." (PMID 35573654, 2022). "We found that the ‘immune response’ genes enriched in the known liver cancer gene set and two known liver cancer genes (CCL5 and CXCL12) were associated with the enriched gene set (p < 10−4, Fisher's Exact Test)." (PMID 27220887, 2016). "Furthermore, it inhibits the CXCL12-induced invasion of liver cancer cells." (PMID 38920657, 2024). "CXCL12 is a ligand of CXCR4, and the activation of CXCL12/CXCR4 makes M2 polarized macrophages promote liver cancer metastasis by secreting VEGF." (PMID 37511481, 2023). "In our study, we focused on the effect of the CXCL12/CXCR4 axis on HCC CTCs, from a new perspective, to illustrate the significance of CXCR4 antibody in precision targeted therapy of liver cancer." (PMID 31752959, 2019). "Simultaneously, 3-formylchromone inhibits the expression of Bcl-2, Bcl-xL, Survivin, and Mcl-1 in liver cancer cells, suggesting that 3-formylchromone promotes apoptosis in liver cancer cells by suppressing the STAT3 pathway and weakening CXCL12-driven metastasis." (PMID 38920657, 2024). "Just as monocytes produce migrasomes rich in VEGFA and CXCL12 to promote angiogenesis under physiological conditions, migrasomes from highly metastatic liver cancer cells also have high concentrations of VEGFA, further promoting angiogenesis and distant metastasis in mice with liver cancer." (PMID 40443653, 2025).
lung adenocarcinoma (17 papers, 2011 to 2025). A carcinoma that arises from the lung and is characterized by the presence of malignant glandular epithelial cells. "TGFβ, a widely studied molecule with an important role in regulating the TME, increases the expression of CXCR7, CXCR4, and CXCL12 in lung adenocarcinoma cells." (PMID 33530455, 2021). "Preferential accumulation of CXCR4 positive Treg, and its correlation with tumour CXCL12 expression, has also been previously demonstrated in adenocarcinomas of the lung and malignant mesothelioma." (PMID 21521526, 2011). "However, in lung adenocarcinoma, samples with higher CXCL12 scores tended to show a higher stromal-to-tumor T cell density ratio." (PMID 40849508, 2025). "Thus CXCL12, which binds to its cognate receptor CXCR4 expressed by Treg, has been implicated in the recruitment of Treg in a number of tumours including ovarian cancer, adenocarcinoma of the lung, malignant mesothelioma, and the myelodysplastic syndromes." (PMID 21521526, 2011). "Sex differences in ERβ, CXCL12, and CXCR4 expression have also been demonstrated in lung adenocarcinomas, with tumors from premenopausal women having greater expression than tumors from postmenopausal women and men." (PMID 41463203, 2025). "Cell studies of lung adenocarcinoma have revealed that estrogen can induce overexpression of CXCR4, which could support tumor growth and metastasis through the CXCL12/CXCR4 pathway." (PMID 41463203, 2025). "The authors also observed that CXCL12 correlated with a higher degree of tumor inflammation and suggested that the concomitant presence of activated TILs CD4+CXCR4+ CD69+ might influence tumor progression by shaping the immune cell population infiltrating lung adenocarcinomas." (PMID 35740564, 2022).
myocardial ischemia (17 papers, 2009 to 2024). A disorder of cardiac function caused by insufficient blood flow to the muscle tissue of the heart. "The CXCL12/CXCR4 axis attaches great importance to myocardial repair after myocardial ischemia/reperfusion injury." (PMID 36131165, 2023). "Numerous studies have revealed that myocardial ischemia significantly upregulates CXCL12 which then exerts a protective effect through CXCL12/CXCR4 signaling on resident cardiomyocytes." (PMID 31385396, 2019). "For example, the CXCL12/CXCR4 axis exerts cardioprotective effects after myocardial ischemia by enhancing the incorporation of progenitor cells in the infarcted region and promoting survival of cardiomyocytes." (PMID 26347749, 2015). "CXCR4 and its ligand CXCL12 are expressed in cardiac myocytes and fibroblasts, and myocardial ischemia significantly upregulates CXCL12." (PMID 24966838, 2014). "However, when mice were treated with roxadustat in the presence of myocardial ischemia, we observed a significant increase in mRNA levels for CXCL12, CXCR4, and ACKR3." (PMID 38994928, 2024).
triple-negative breast carcinoma (17 papers, 2014 to 2025). An invasive breast carcinoma which is negative for expression of estrogen receptor (ER), progesterone receptor (PR), and human epidermal growth factor receptor 2 (HER2). "In triple-negative breast cancer, CAFs secrete CXCL12 within the primary tumor, promoting the expansion of cancer cell clones that will preferentially metastasize to the CXCL12-rich bone marrow environment." (PMID 38506114, 2024). "Nano-delivery of IL10 trap and CXCL12 trap significantly reduced tumor growth and immunosuppressive cells and prolonged survival in orthotopic 4T1 triple-negative breast cancer models." (PMID 35079936, 2022). "MLK3 has been also shown to be involved in the invasion of triple-negative breast cancer (TNBC) cells triggered by C-X-C chemokine receptor type 4 (CXCR4)/stromal cell-derived factor 1 (CXCL12)." (PMID 35409206, 2022). "By concurrently disengaging the CXCR4/CXCL12-mediated immunosuppressive microenvironment and promoting tumour-specific immunity, this dual-action strategy provides a novel and synergistic approach to target drug resistance in triple-negative breast cancer." (PMID 41002447, 2025). "In triple negative breast cancer patients, high cytoplasmic CXCR4 expression was related to lower distant recurrence and better recurrence-free survival, while high CXCL12 expression was associated with larger tumor size, positive lymph node metastasis, and higher pathologic stage." (PMID 35079936, 2022). "In triple-negative breast cancer, CAFs were described to secrete C-X-C motif chemokine ligand 12 (CXCL12) and insulin-like growth factor-1 (IGF1) factors that promote the expansion of high metastatic clones with high Src activity, a known predictor of bone metastasis." (PMID 32793478, 2020). "Similarly, CXCL12 produced by CAFs mediates bone metastasis of triple-negative breast cancer." (PMID 28356139, 2017). "For example, CAF-derived CXCL12 and insulin-like growth factor 1 (IGF1) can promote the survival and outgrowth of highly invasive and metastatic triple-negative breast cancer cells in the bone marrow." (PMID 28356139, 2017). "Furthermore, LPAR1 heterodimerises with C-X-C chemokine receptor type 4 (CXCR-4) and inhibits CXCL12-induced CXCR4 signalling, while LPA/LPAR1 blocks CXCL12/CXCR4-induced migration of triple-negative breast cancer cells." (PMID 38607068, 2024). "The CXCL12-enhanced chemotaxis of triple negative breast cancer cells (MDA-MB-231) was inhibited in a mixture of CXCL4 and CXCL12 chemokines, and CXCL4 counteracted CXCL12-induced ERK (extracellular signal-regulated kinase) phosphorylation in lymphatic and microvascular endothelial cells." (PMID 37511398, 2023). "In triple-negative breast cancer, the tumor subtypes rich in CAFs are more prone to bone metastasis, which is related to CXCL12 (C-X-C motif chemokine ligand 12) and IGF1 (insulin-like growth factor-1) cytokines and the CCL4-CCR5 (C-C motif chemokine ligand 4-C-C motif chemokine receptor 5) axis." (PMID 34877360, 2021).